MSLN (mesothelin)
Diseases named in the same sentence as MSLN in open-access papers (continued):
Sharing a sentence is not in itself a finding about the gene and the disease.
tumor (continued). "Researchers also demonstrated the antitumor activity of anti-MSLN CAR-T cells based on the clinical and laboratory evidence such as specific and potent lysis capacity of anti-MSLN CAR-T cells resulting in a decrease in the tumor cells in a patient’s ascites." (PMID 28466386, 2017). "Immunohistochemistry staining of the liver and lung tissue sections with anti-human MSLN antibody confirmed that the tumor nodules were of human origin." (PMID 28288645, 2017). "Secondly, genetic knockdown of MSLN significantly reduced anchorage-independent cell growth, tumor sphere formation, cell adhesion, migration and invasion in vitro, as well as tumor formation and metastasis in vivo." (PMID 28288645, 2017). "Knockdown of MSLN in these cell lines reversed their malignant phenotype as indicated by soft agar colony formation, tumor sphere formation, and cell migration and invasion assays as well as tumor formation in animals." (PMID 28288645, 2017). "To verify the in vitro observations, we conducted in vivo experiments assessing the effects of MSLN knockdown on tumor formation and metastasis using a xenograft mouse model." (PMID 28288645, 2017). "Mesothelin overexpression in approximately 50% of advanced gastroesophageal cancers was recently reported, where expression levels were shown to increase with tumour staging." (PMID 29113296, 2017). "Mesothelin has attracted much interest as a tumor specific antigen; it has been reported to promote tumor development and to be a good target for cancer treatment." (PMID 26931187, 2016). "Surprisingly overexpression of mesothelin inhibited tumor formation in vivo in immunocompetent mice." (PMID 26931187, 2016). "Our data are in contrast to data reported on human mesothelin in the MIA PaCa-2, human tumor cell line expressing tumors in nude mice, and on mouse mesothelin in nude mice where mesothelin overexpression correlated with increased tumor growth." (PMID 26931187, 2016). "Mouse mesothelin is similar to human mesothelin in biochemical characteristics, tumor expression and tissue distribution." (PMID 26931187, 2016). "The experiment in vivo further showed that up-regulation of Sulf-1 with the attendant downregulation of mesothelin delayed tumor growth and decreased lymph node metastasis." (PMID 27626699, 2016). "The aim of this imaging study was to assess biodistribution and tumor uptake, and the relationship between tumor uptake and MSLN expression, as well as response to treatment." (PMID 27252651, 2016). "Mesothelin (Msln) is a 40kDa cell membrane glycoprotein and is known to act as a tumor promoter gene in various malignancies." (PMID 27626699, 2016). "The tumor cells overexpressing mesothelin also appeared to have increased production of extracellular matrix." (PMID 26931187, 2016). "A myriad of cytokines, chemokines, stromal, and innate and adaptive immune cells interact to create the tumor microenvironment in vivo: how mesothelin affects these complex interactions and tumor growth requires further study." (PMID 26931187, 2016). "Human mesothelin has been well characterized, and the role of human mesothelin in tumor growth and treatments in immunocompromised mice has been explored." (PMID 26931187, 2016). "This technique was used in a database comprising 19,746 tumors to identify for 41 tumor types the percentage of samples with an overexpression of MSLN compared to a normal background." (PMID 26172299, 2015). "The resulting Fv (hYP218) has the same functional binding affinity for mesothelin-expressing tumor cells." (PMID 25996440, 2015). "This highly facilitates prioritization of tumor types for future research in which the clinical benefit of targeting MSLN with immunotoxins or ADCs." (PMID 26172299, 2015). "The percentages of tumor samples that showed MSLN over-expression or predicted MSLN amplification differ between the two techniques, with on average higher percentages for the IHC data." (PMID 26172299, 2015).
tumor (continued). "In vivo, tumor xenograft studies showed that amatuximab plus chemotherapy led to a greater reduction in the growth of mesothelin-expressing tumors than either amatuximab or chemotherapy alone." (PMID 25502863, 2015). "Immunohistochemical examination of mesothelin expression in surgically resected tumor specimens is clinically useful for assessing the prognosis and for deciding on the necessity of additional treatment following surgical procedures in patients with IPMN." (PMID 25789005, 2015). "The concentration of shed mesothelin correlates with tumor size and binding of amatuximab to shed antigen decreases available antibody for tumor uptake." (PMID 25756664, 2015). "We identified 14 published papers in which IHC staining for MSLN was described for a total of 2,846 tumor samples." (PMID 26172299, 2015). "Mesothelin staining was present in tumor nests and most strongly expressed at the apical side of tumor cells surrounding ducts." (PMID 26536664, 2015). "The incidence of luminal membrane mesothelin expression was correlated with the histological classification of the tumor (P=0.022) and the recurrence rate (P=0.0030)." (PMID 25789005, 2015). "The membrane bound glycoprotein mesothelin (MSLN) is a highly specific tumor marker, which is currently exploited as target for drugs." (PMID 26172299, 2015). "Strong membranous and cytoplasmic mesothelin expression was seen in more than 90% of tumor cells from the right pleural-based mass." (PMID 25756664, 2015). "Mesothelin is a glycoprotein normally expressed in mesothelial cells but highly overexpressed in a number of different tumor types making it a promising target for tumor immunotherapy." (PMID 24860789, 2014). "An increase in the serum level of N-ERC/mesothelin correlated with increased tumor size (R = 0.89665, P<0.0001, n = 14)." (PMID 25347530, 2014). "Several published studies have evaluated MSLN expression in different tumor types, using various scoring systems to quantify the immunohistochemical expression of MSLN." (PMID 25506917, 2014). "MUC16-mesothelin interaction allows tumor cells to bind to themselves (likely increasing tumor mass at metastatic sites) and also allows attachment of ovarian cancer cells to the mesothelial lining." (PMID 24886523, 2014). "P4 scFv directed against MSLN, a surface antigen overexpressed on several types of tumor cells, is used as a means of targeting the immunotherapeutic agent." (PMID 24565018, 2014). "We demonstrated in vitro that the scFvMTBHsp70 fusion protein bound to the tumor cells used in this study through the interaction of scFv with MSLN on the surface of these cells, and induced maturation of bone marrow-derived DCs." (PMID 24565018, 2014). "Another important aspect of the mesothelin/MUC16 interaction is its contribution to both homotypic (tumor cell-tumor cell) and heterotypic (tumor cell-mesothelial cell) cell interactions." (PMID 24447304, 2014). "Nevertheless, these data provide useful information on the shedding rate: Assuming the same permeability as for the A431/H9 tumor, the experimental shed antigen levels can be obtained only when the shedding rate is much smaller than that of mesothelin." (PMID 25343405, 2014). "The expression levels of KOC, S100P and mesothelin were high in tumour tissue compared with normal tissue." (PMID 25071419, 2014). "Several studies have investigated how changes in expression of the MSLN gene can alter tumor growth, progression or invasiveness to produce a more aggressive tumor phenotype." (PMID 25118887, 2014). "Membrane-bound MSLN is also released into body fluids and its use as a potential serum tumor marker is currently under investigation." (PMID 25506917, 2014). "Soluble mesothelin-related protein (SMRP), megakaryocyte potentiating factor (MPF), and mesothelin (MSLN) variants are the most commonly used serological tumor antigens for MM detecting." (PMID 23977302, 2013).
tumor (continued). "Most of these genes (MUC12, S100P, GSTT1, USP9Y, MSLN and so on) are involved in tumor initiation, progression or metastasis." (PMID 23787019, 2013). "In contrast, ASPC-1-shRNA mesothelin cells with reduced mesothelin expression showed a significant reduction in tumor volume compared with mock control cells (p < 0.01)." (PMID 23034174, 2012). "Vaccination with chimeric virus-like particles that contain human mesothelin substantially inhibited tumor progression in C57BL/6 J mice." (PMID 23034174, 2012). "The very limited distribution of MSLN on normal tissues portrays MSLN a suitable candidate for tumor-specific therapy." (PMID 22485139, 2012). "In contrast, in the tumor ovaries that exhibited mesothelin mRNA expression, intense staining was seen in surface epithelial cells, in the ovarian stroma and in aggregates of tumor cells." (PMID 21801396, 2011). "The difference in mesothelin mRNA expression between normal and tumor containing ovaries estimated from normalized contour quantities of bands was significant (p < 0.0001, Fishers exact test)." (PMID 21801396, 2011). "Well-studied tumor antigens such as mesothelin, CEA, and folate receptor are displayed to the cell surface through a GPI-anchor." (PMID 22163010, 2011). "Tumor overexpression of glycoproteins such as mesothelin has mainly been used as a mean of biomarker identification, but the study of their functional roles during cancer development remains preliminary." (PMID 22163010, 2011). "Enrichment of tumor antigens such as melan-A, Silv, carcinoembryonic antigen (CEA), and mesothelin is observed in tumor-derived exosomes when compared with whole cell lysates." (PMID 22190973, 2011). "To address these questions, we used soluble mesothelin from patient samples, tumor cell lines and cells transfected with a GPI-truncated form of mesothelin." (PMID 22163010, 2011). "We further demonstrated that the interaction of tumor-released mesothelin with mannose receptor expressed by macrophages was mediated, at least in part, by mesothelin GPI anchor." (PMID 22163010, 2011). "This antibody both induces ADCC (antibody-dependent cellular cytotoxicity) against tumor cells that express mesothelin as well as blocks the MUC16/mesothelin interaction." (PMID 20350313, 2010). "Although mesothelin has been documented as a tumour-associated marker in EOC, analyses focussing on the correlation between mesothelin expression and clinicopathological variables and clinical outcomes have seldom been carried out." (PMID 19293794, 2009). "Importantly, there was an enhanced MSLN expression in TNBC liver metastases compared with primary tumor tissues." (PMID 41513618, 2026). "Evidence from clinical and experimental studies indicates that MSLN contributes to tumor progression through interactions with CA125, promotion of cell adhesion and peritoneal metastasis, activation of oncogenic signaling pathways, modulation of immune responses, and development of chemoresistance." (PMID 42279275, 2026). "The MSLN expression on tumor cell surfaces was analyzed by flow cytometer." (PMID 40366419, 2025). "Indeed, ABBV-428 efficiently induces T-cell activation and reduced tumor growth in a MSLN-dependent manner." (PMID 41335396, 2025). "In summary, MSLN drives the progression of malignant tumors through multiple mechanisms, including regulating epithelial-mesenchymal transition, inducing chemotherapy resistance, and remodeling the tumor microenvironment." (PMID 41400642, 2025). "Researchers found that 68% of the tumor samples had positive MSLN expression." (PMID 41400642, 2025). "Traditional immunohistochemical or RNA sequencing methods primarily reflect overall MSLN expression levels in tumor tissues and fail to distinguish whether expression originates from tumor cells themselves or other cell subpopulations within the tumor." (PMID 41400642, 2025).
tumor (continued). "This includes targets such as mesothelin and cadherin 6; the identification of these targets reflects an enhanced understanding of tumor biology and supports the need for personalized treatment strategies that address the unique characteristics of each patient's cancer." (PMID 41347223, 2025). "Furthermore, MSLN-directed chimeric antigen receptor T cells were shown to induce an effective anti-tumor response in preclinical models of PDAC." (PMID 40266223, 2025). "Additionally, MSLN increases the level of IL-6 secreted by tumor cells through the NF-κB signaling pathway." (PMID 41400642, 2025). "Third, we focused on MSLN-positive tumor cell lines (such as HGC27, MKN45, NCI-N87, and CFPAC-1) to assess antitumor efficacy, concentrating on gastrointestinal tumors, which may limit the generalizability of our findings." (PMID 41436559, 2025). "Mesothelin (MSLN) is a glycosylphosphatidylinositol (GPI)-anchored membrane protein that promotes malignant behaviors including tumor cell proliferation, migration and immune evasion through activation of multiple signaling pathways, such as MAPK/ERK and PI3K/AKT." (PMID 41400642, 2025). "Wang and colleagues developed an anti-mesothelin CAR T that co-expresses the chemokine receptor CCR2b for treatment of preclinical models of non-small-cell lung carcinoma which demonstrated superior tumor infiltration compared to the Msln-CAR alone." (PMID 40636106, 2025). "Notably, anti-MSLN CAR-like NK cells demonstrated a more significant advantage in inhibiting tumor growth than MSLN×CD16A combined with CIML NK cell therapy did (P < 0.05), with this trend strengthening over time." (PMID 41436559, 2025). "A potential explanation is that MSLN may regulate type I collagen in the tumor microenvironment to maintain its structural integrity, thereby limiting the invasion of malignant cells to some extent." (PMID 41400642, 2025). "Mesothelin may be involved in tumor initiation, progression, invasion, and metastasis through multiple signaling pathways." (PMID 40697656, 2025). "Importantly, our study provides the first evidence that MSLN can be transferred from tumor cells to immune cells via EVs." (PMID 41226368, 2025). "MSLN can also enhance the adhesion between tumor cells and mesothelial cells." (PMID 41400642, 2025). "Beyond mechanistic studies, another key challenge for the clinical translation of MSLN is that its functions may vary across different tumor types." (PMID 41400642, 2025). "Importantly, there was a significant negative correlation between MSLN expression and the infiltration of CD3+CD8+ T cells (p = 0.0008); and the patients with high MSLN expression in tumor tissue showed poorer 5‐years survival (p = 0.0323)." (PMID 39887656, 2025). "These agents could potentially be repurposed or tested in PDAC settings to evaluate whether pharmacological MSLN inhibition induces tumor senescence and improves therapy response." (PMID 40563707, 2025). "Nanoparticle-mediated drug delivery systems or ligand-targeted approaches (e.g., using MUC16-binding peptides) could enhance the selective inhibition of MSLN at the tumor site, minimizing off-target effects." (PMID 40563707, 2025). "This enhanced maturation can be attributed to the enhanced tumor cell lysis induced by both HSV-MSLN and MSLN-CAR T cells, which release inflammatory mediators that synergize with the virus-derived mediators to significantly enhance DC maturation and activation." (PMID 40366419, 2025). "The findings demonstrate that MSLN-targeted CAR-T cells with PD-1 silencing have enhanced anti-tumor activity, indicating that silencing genes to target particular immune checkpoints may enhance CAR-T cell therapy for various types of cancer." (PMID 40227616, 2025).
tumor (continued). "This strategy has shown superior efficacy compared to bsAbs directed against the membrane-distal region of MSLN (MSLNMDR) that is often shed into the bloodstream or present in non-tumor tissues, potentially leading to on-target/off-tumor toxicity (NCT06756035, NCT06523803, NCT06255665)." (PMID 41335396, 2025). "A recent study suggests that soluble MSLN (sMSLN) in plasma may bind to anetumab, impairing its delivery to tumor tissues and thus diminishing its efficacy." (PMID 40904706, 2025). "Mesothelin is a glycoprotein overexpressed in various malignancies, making it an attractive target for therapies designed to deliver cytotoxic agents directly to tumor cells while minimizing damage to normal tissues." (PMID 41347223, 2025). "Moreover, this research observed by in vivo imaging that the infused NKT and γδT cells selectively homed to the tumor site, providing an additional advantage for their synergistic action in the presence of MSLN/CD3 BsAb." (PMID 39995672, 2025). "In our study, we utilized the 1% O2 condition to mimic the hypoxic environment, and observed that hypoxia severely impaired survival, proliferation, memory phenotypes, cytokine production, and anti-tumor cytotoxicity of both anti-MSLN and anti-CD70 CAR-T cells." (PMID 41199316, 2025). "Furthermore, the anti-tumor efficacy of CD28-PD1 CRS expressed in TRuCT cells was validated in mice bearing MSLN-positive tumors, and this strategy is currently being investigated in a phase I/II clinical trial (NCT05451849)." (PMID 41335396, 2025). "Notably, NKG2D/CD28& MSLN CAR-T cell group showed enhanced tumor suppression, with a significant difference observed when compared to the traditional MSLN CAR-T cell group." (PMID 40181405, 2025). "The functionality of such antibodies, however, was not evaluated in this study and could be the subject of an interesting analysis for the future to confirm the ability of the antibodies to bind MSLN-expressing tumor cells." (PMID 40266223, 2025). "Clinical studies have demonstrated that MSLN is significantly overexpressed in various tumor tissues, while in healthy tissues, it is primarily found on the surface of mesothelial cells, with minimal expression in critical organs such as the lungs, kidneys, and liver." (PMID 41400642, 2025). "Clinical trials targeting mesothelin (MSLN) illustrate this challenge of off-tumor toxicity." (PMID 41154636, 2025). "Based on the high expression of MSLN in apCAFs, we hypothesized that αMSLN treatment could eliminate apCAFs within the tumor." (PMID 39887656, 2025). "Among the most promising approaches are those based on CAR-T cells, in which patient-derived T lymphocytes are engineered to express chimeric antigen receptors recognizing MSLN and, in some cases, to target multiple antigens within the tumor microenvironment (TME)." (PMID 41335396, 2025). "hCD45+ cells colocalized with MSLN+ tumor cells, suggesting possible direct interaction." (PMID 40315330, 2025). "In addition, radiation therapy can induce the expression of tumor antigens such as mesothelin and enhance the anti-tumor effects of CAR-T cells." (PMID 40072049, 2025). "In ovarian cancer, tumor-released mesothelin, which is linked to a glycosylphosphatidylinositol (GPI) anchor, binds to MR on macrophages, driving their polarization toward the TAM phenotype, which supports tumor growth and suppresses the immune response." (PMID 40330466, 2025). "This hypothesis stemmed from the observation that the PDAC patients with high MSLN expression in tumor biopsies showed unusually low levels of MSLN in the bloodstream, suggesting that shed MSLN was somehow retained within the TME." (PMID 41335396, 2025). "Therefore, further studies are necessary to clarify the definition of “MSLN-positive” and to adopt more comprehensive methods for evaluating actual MSLN expression levels in tumor tissues." (PMID 41400642, 2025).